GPIHBP1 (glycosylphosphatidylinositol anchored high density lipoprotein binding protein 1)
Diseases named in the same sentence as GPIHBP1 in open-access papers (continued):
Sharing a sentence is not in itself a finding about the gene and the disease.
pancreatitis (9 papers, 2007 to 2025). Inflammation of the pancreas. "One patient with severe type 5 hyperlipoproteinemia (MIM 144650), fasting chylomicronemia and relapsing pancreatitis resistant to standard therapy was found to be homozygous for a novel GPIHBP1 missense variant, namely G56R." (PMID 17883852, 2007). "FCS due to biallelic LPL, APOC2, GPIHBP1, or LMF1 variants accounted for <5% of cases and showed extreme TG elevations (>2800 mg/dL) with pancreatitis prevalence (>70%)." (PMID 41300829, 2025). "In four of the 28 patients with primary hypertriglyceridemia a possible genetic cause of the sHTG was found: Homozygosity for a deletion comprising exons 3 and 4 in GPIHBP1 was found in two women who both had been hospitalized for pancreatitis several times." (PMID 28606150, 2017). "The proband, a homozygote for GPIHBP1 G56R, had relapsing pancreatitis beginning at age 22 and was documented on numerous occasions to refractory fasting chylomicronemia, even with fat restriction." (PMID 17883852, 2007). "Carriers of APOA5, GPIHBP1, or LMF1 variants exhibited intermediate TG levels (1800–2500 mg/dL) and substantial pancreatitis risk, whereas APOB and APOC3 variant carriers had milder TG elevations (500–1500 mg/dL) but were more frequently associated with hepatic steatosis and metabolic comorbidities." (PMID 41300829, 2025). "Patients with GPIHBP1 deficiency express a similar phenotype as patients with LPL deficiency, such as severe chylomicronemia (plasma TG levels above 1,500 mg/dl (16.9 mmol/L) presented already in childhood and high risk of pancreatitis." (PMID 36051701, 2022).
acute pancreatitis (7 papers, 2014 to 2025). An acute inflammatory process that leads to necrosis of the pancreatic parenchyma. "We report the successful management of a 35-year-old pregnant woman carrying a novel homozygous frameshift mutation c.48_49insGCGG (p.P17A fs*22) in the GPIHBP1 gene with previous severe episodes of acute pancreatitis triggered by pregnancy, resulting in adverse obstetrical outcomes." (PMID 32375710, 2020). "We found that plasma triglyceride concentrations were dramatically lowered in Gpihbp1−/− mice after 6 days of fenofibrate administration before acute pancreatitis was induced." (PMID 31570698, 2019). "Meanwhile, in the acute pancreatitis model, free fatty acids (FFAs) in the pancreas of Gpihbp1−/− mice were greater than in ApoC3-tg mice." (PMID 31570698, 2019). "Moreover, another unrelated HTG individual, who had the compound heterozygote L279V and a known GPIHBP1 mutation, suffered from a severe HTG and acute pancreatitis." (PMID 24646025, 2014). "Chinese patients with HTG-associated acute pancreatitis (HTG-AP) were screened for rare nonsense, frameshift, missense or canonical GT-AG splice site variants in LPL and four other lipid metabolism-related genes (APOC2, APOA5, GPIHBP1 and LMF1) by Sanger sequencing." (PMID 37550668, 2023).
atherosclerosis (6 papers, 2011 to 2023). A disease characterized by the build-up of fatty material and calcium deposition in the arterial wall resulting in partial or complete occlusion of the arterial lumen. "The proatherosclerotic effects of GPIHBP1 deficiency are probably caused by the markedly elevated levels of CM/VLDL, which exacerbate atherosclerosis through increasing the formation of TGRL remnants and generation of proatherogenic lipid products." (PMID 35693558, 2022). "Based on genetically modified mouse models, such as LPL−/−, GPIHBP1−/−, and ApoC3 transgenic mice, triglycerides were demonstrated to promote atherosclerosis." (PMID 34796210, 2021). "In a previous study,we reported the occurrence of spontaneous atherosclerosis in LPL deficient HTG mice older than 15 months,which was further confirmed by a recent report on atherogenicity in Gpihbp1-deficient HTG mice." (PMID 21980507, 2011).
hyperlipidemia (6 papers, 2014 to 2022). "Meanwhile, some studies on hyperlipidemia showed that GPIHBP1 served as the transporter and the platform for the lipoprotein lipase-mediated lipolysis processing." (PMID 25810903, 2014). "Two patients with other five family members were included in this study for DNA-sequences of hyperlipidemia-related genes (such as LPL, APOC2, APOA5, LMF1, and GPIHBP1) and 43 healthy individuals and 70 HTG subjects were included for the screening of LPL gene mutations." (PMID 24646025, 2014).
diabetes (5 papers, 2020 to 2026). "Following diabetes, cardiac GPIHBP1 gene and protein expression also increase with an associated augmentation of coronary LPL activity." (PMID 39081272, 2024). "GPIHBP1 demonstrated moderate discriminative performance for the presence of diabetes, diabetic neuropathy and nephropathy." (PMID 42194055, 2026). "Further studies are required to ascertain the significance of GPIHBP1 as a biomarker and therapeutic target in the management of obesity, diabetes, and dyslipidemia." (PMID 37448184, 2023). "In hearts from animals with diabetes, GPIHBP1 gene and protein expression increased with exclusive EC localization." (PMID 34356640, 2021). "Given that high glucose can stimulate the secretion of both forms of Hpa, this could be one mechanism by which the EC can increase GPIHBP1 to accelerate FA delivery to the cardiomyocytes after diabetes." (PMID 39081272, 2024). "As this effect was also duplicated by active heparanase, high glucose, together with its secretion of heparanase, could be the unforeseen mechanism by which the EC can increase its expression of GPIHBP1 to augment the supply of FAs following diabetes." (PMID 34356640, 2021).
type 2 diabetes (5 papers, 2012 to 2026). "To further explore the role of insulin in peripheral lipolysis, we studied Gpihbp1 mRNA and protein expression in a well-established type 2 diabetic mouse model, the insulin resistant Leprdb/db and control Leprdb/m mice." (PMID 30408040, 2018). "Next, we assessed visceral adipose tissue GPIHBP1 protein expression in type 2 diabetes Leprdb/db mouse model as well as in subjects with ranging levels of insulin resistance." (PMID 30408040, 2018). "Our prior work indicated that circulating GPIHBP1 levels are associated with the incidence of microvascular complications in women with type 2 diabetes, irrespective of TG levels." (PMID 41142641, 2025). "Whether Glycosyl Phosphatidyl Inositol high density lipoprotein binding protein 1 (GPIHBP1) function is impaired and may underlie the hyperTG phenotype observed in type 2 diabetes is not yet established." (PMID 30408040, 2018). "In contrast, circulating GPIHBP1 levels are not altered in type 2 diabetes patients with higher serum triglyceride levels, whereas they are elevated in type 2 diabetes patients with diabetic retinopathy and nephropathy." (PMID 37448184, 2023). "In patients with type 2 diabetes, the circulating GPIHBP1 levels might not correlate well with TRL, and rather well‐reflect the microvascular complications, such diabetic retinopathy and diabetic kidney disease." (PMID 37448184, 2023). "In patients with type 2 diabetes, the circulating GPIHBP1 levels might not correlate well with triglyceride‐rich lipoproteins, and rather well‐reflect the microvascular complications, such diabetic retinopathy and diabetic kidney disease." (PMID 37448184, 2023).
breast carcinoma (3 papers, 2019 to 2025). "GPIHBP1 is reported to be downregulated in breast cancer relative to precancerous tissues, and to facilitate TRL processing in glioma cells." (PMID 40450000, 2025). "The glycosylphosphatidylinositol high-density lipoprotein binding protein 1 (GPIHBP1) acts to chaperone secreted LPL and interact in fatty acids and breast cancer." (PMID 31182966, 2019). "Finally, 6 upregulated DEGs (CST2, DRP2, CLEC5A, SCD, KIAA1211, DTL) and 6 downregulated DEGs (STAC2, BTNL9, CA4, CD300LG, GPIHBP1 and PIGR), were confirmed in a quantitative real time PCR comparison of breast cancer and paracancerous breast tissues from 8 clinical specimens." (PMID 31182966, 2019).
glioma (3 papers, 2019 to 2025). A benign or malignant brain and spinal cord tumor that arises from glial cells (astrocytes, oligodendrocytes, ependymal cells). "The expression of GPIHBP1 (a hallmark of capillary endothelial cells in peripheral tissues) in gliomas provides biochemical support for the notion that glioma capillaries resemble capillaries in peripheral tissues." (PMID 31169500, 2019). "Mice harboring gliomas (after three weeks of growth) were injected intravenously with an Alexa Fluor 647–conjugated antibody against mouse GPIHBP1 (11A12)." (PMID 31169500, 2019). "The factors that regulate Gpihbp1 expression in the capillary endothelial cells of peripheral tissues and gliomas are incompletely understood." (PMID 31169500, 2019). "In Gpihbp1-deficient mice, GLUT1 expression was detectable in the capillaries of gliomas and normal brain." (PMID 31169500, 2019). "Additional immunohistochemistry studies on mouse gliomas revealed that LPL colocalizes with GPIHBP1 on glioma capillaries, just as LPL colocalizes with GPIHBP1 in the capillaries of heart and brown adipose tissue." (PMID 31169500, 2019). "As expected, the presence of recombinant GPIHBP1 eliminated binding of the GPIHBP1-specific mAbs to glioma capillaries." (PMID 31169500, 2019). "Confocal immunofluorescence microscopy studies on glioma and normal brain from wild-type and Gpihbp1–/– mice, along with the brain from an Lpl–/– mouse carrying a skeletal muscle–specific human LPL transgene (MCK)." (PMID 31169500, 2019). "Using standard immunohistochemistry procedures, we documented GPIHBP1 expression in capillary endothelial cells of human gliomas and CT-2A-derived mouse gliomas." (PMID 31169500, 2019). "NanoSIMS imaging revealed that GPIHBP1 expression in gliomas facilitates TRL processing and provides a source of lipid nutrients for glioma cells." (PMID 31863022, 2019). "To be confident in the specificity of the antibodies, we performed studies in which recombinant human GPIHBP1 was added to the GPIHBP1-specific mAbs before incubating the solution with the glioma sections." (PMID 31169500, 2019). "After three weeks of glioma growth, mice were anesthetized and injected via the tail vein with an Alexa Fluor 647–labeled antibody against mouse GPIHBP1 (11A12; red)." (PMID 31169500, 2019). "Another possibility is that GPIHBP1 expression is stimulated by the expression of VEGF that is produced by glioma cells." (PMID 31169500, 2019). "We have relatively few insights into the molecular basis for GPIHBP1 expression in glioma capillaries." (PMID 31169500, 2019). "LPL was not present in the capillaries of the normal brain or in the capillaries of gliomas from Gpihbp1–/– mice." (PMID 31169500, 2019). "In the current study, we sought to determine whether glioma capillaries express GPIHBP1 and, if so, whether it binds LPL and facilitates TRL margination and the lipolytic processing of TRLs." (PMID 31169500, 2019). "Lipoprotein lipase (LPL) colocalizes with GPIHBP1 in glioma capillaries." (PMID 31169500, 2019). "However, a recent study showed that GPIHBP1 is expressed in the capillaries of mouse and human gliomas, and seems to be involved in LPL production." (PMID 31863022, 2019). "Given the presence of GPIHBP1-bound LPL on glioma capillaries, we suspected that we might find evidence of TRL margination and processing in gliomas." (PMID 31169500, 2019). "We sought to determine whether GPIHBP1, despite its complete absence from the capillaries of the brain, might nevertheless be expressed in the capillaries of gliomas." (PMID 31169500, 2019). "To determine whether LPL is bound to GPIHBP1-expressing capillaries of gliomas, we performed immunohistochemical studies, taking advantage of an affinity-purified goat antibody against mouse LPL." (PMID 31169500, 2019). "GPIHBP1 expression in the endothelial cells of several human gliomas." (PMID 31169500, 2019).
glioma (continued). "The expression of GPIHBP1 in glioma capillaries was intriguing, but the crucial issue is whether LPL would be bound to the GPIHBP1." (PMID 31169500, 2019). "Thus, GPIHBP1 expression in gliomas facilitates TRL processing and provides a source of lipid nutrients for glioma cells." (PMID 31169500, 2019). "GPIHBP1 is expressed by capillary endothelial cells in mouse gliomas." (PMID 31169500, 2019). "Importantly, the GPIHBP1 in glioma capillaries captures locally produced LPL." (PMID 31169500, 2019). "GPIHBP1 expression in glioma capillaries could also be detected by immunoperoxidase staining." (PMID 31169500, 2019). "It would also be desirable to determine whether the uptake of TRL-derived nutrients in gliomas correlates with the levels of GPIHBP1 and LPL in glioma capillaries (as quantified with LPL- and GPIHBP1-specific antibodies tagged with different lanthanide metals)." (PMID 31169500, 2019). "If GPIHBP1 were to be expressed in glioma capillaries, it could be relevant to glioma metabolism." (PMID 31169500, 2019). "We hypothesized that GPIHBP1-expressing endothelial cells of gliomas could capture LPL." (PMID 31169500, 2019). "The GPIHBP1 in glioma capillaries could be detected with all three GPIHBP1-specific mAbs." (PMID 31169500, 2019). "In addition, a localized injection of GPIHBP1-specific monoclonal antibodies conjugated to chemotherapeutic agents into gliomas might be useful in targeting tumor vasculature." (PMID 31169500, 2019). "Glioma and brain sections (10-μm-thick) were fixed with 3% PFA and then stained with a mAb against mouse GPIHBP1 (11A12; green), a goat antibody against mouse LPL (red), and a rabbit antibody against CD31 (white)." (PMID 31169500, 2019). "Documenting GPIHBP1 and LPL in glioma capillaries, combined with the discovery that TRL-derived nutrients are taken up and utilized by glioma cells, opens a new chapter in glioma metabolism research." (PMID 31169500, 2019). "The GPIHBP1 might capture locally produced LPL, allowing for TRL margination and TRL processing, and thereby providing a source of lipid nutrients for glioma cells." (PMID 31169500, 2019). "GPIHBP1 was present in the capillaries of mouse gliomas (blue) but absent from the capillaries of the normal brain." (PMID 31169500, 2019). "The binding of LPL to GPIHBP1 was specific: the LPL-specific goat antibody did not detect LPL in the capillaries of gliomas in Gpihbp1–/– mice, nor did it detect any LPL in macrophages or hippocampal neurons of Lpl–/–MCK-hLPL mice." (PMID 31169500, 2019). "Confocal microscopy images of a BFP-tagged CT-2A glioma implanted in a ROSAmT/mG::Pdgfb-iCreERT2 mouse, revealing the expression of GPIHBP1 in capillary endothelial cells of the glioma but not those of normal brain." (PMID 31169500, 2019). "The colocalization of GPIHBP1 and LPL in the capillaries of gliomas implied that we might find evidence for TRL margination and processing in these tumors." (PMID 31169500, 2019). "GPIHBP1 expression in glioma capillaries did not appear to correlate with glioma grade, 1p/19q co-deletions, or IDH1 mutations." (PMID 31169500, 2019). "Immunohistochemical studies on surgically resected gliomas (Gliomas 1, 5, 9) and non-diseased human frontal lobe (n = 3), revealing GPIHBP1 expression in capillaries of gliomas but not in frontal lobe specimens." (PMID 31169500, 2019). "Expression of GPIHBP1 and GLUT1 in the endothelial cells of mouse gliomas." (PMID 31169500, 2019). "GPIHBP1 is absent from the capillaries of the brain, which uses glucose for fuel; however, GPIHBP1 is expressed in the capillaries of mouse and human gliomas." (PMID 31169500, 2019). "Despite the absence of GPIHBP1 expression in brain capillaries, we were curious about whether GPIHBP1 might be expressed in the capillaries of gliomas." (PMID 31169500, 2019). "GPIHBP1 was present on endothelial cells of the glioma (blue) but was absent from normal brain." (PMID 31169500, 2019).
glioma (continued). "GPIHBP1 expression was detected in gliomas but was absent in the normal brain." (PMID 31169500, 2019). "However, a recent study found that Gpihbp1 transcript levels in rat aortic endothelial cells are upregulated by vascular endothelial growth factor (VEGF), an angiogenic factor known to be expressed at high levels by glioma cells." (PMID 31169500, 2019). "Finally, it would be desirable to investigate whether the presence of GPIHBP1 and LPL in glioma capillaries could be exploited for patient care." (PMID 31169500, 2019). "One possibility is that the absence of a blood–brain barrier in glioma capillaries permits the exposure of endothelial cells to a paracrine factor that activates GPIHBP1 expression." (PMID 31169500, 2019). "GPIHBP1 was detected in endothelial cells of the gliomas, colocalizing with EGFP (brain endothelial cells), but GPIHBP1 was absent from capillaries in the adjacent normal brain." (PMID 31169500, 2019). "LPL colocalizes with GPIHBP1 and CD31 in the capillaries of gliomas; GPIHBP1 and LPL were absent from normal brain capillaries and from glioma capillaries in Gpihbp1–/– mice." (PMID 31169500, 2019).